TGFB1 (transforming growth factor beta 1)
Diseases named in the same sentence as TGFB1 in open-access papers (continued):
Sharing a sentence is not in itself a finding about the gene and the disease.
cancer (continued). "Platelet-derived TGFβ1 can promote an epithelial-mesenchymal transition in cancer cells, an essential step in cancer invasion and metastasis." (PMID 28737696, 2017). "TGFβ1 and cancer-secreted factors significantly reduced sphere formation whereas the use of pharmacological TGFβ inhibitors increased sphere formation." (PMID 28372546, 2017). "For TGFB1 protein, most of cancer tissue attained moderate to strong expression in the cytoplasm, but the protein was less intense in approximately one-fifth of patients and absent in three samples only." (PMID 29104726, 2017). "Following optimization of the autophagy detection system on biochips, the role of TGFβ1 in cancer cell-stroma interaction was tested." (PMID 28515430, 2017). "Integrin activation of TGFβ1 influences cancer progression not only on the luminal component of breast tissue." (PMID 27515461, 2016). "Pathway analysis revealed that lncRNAs upregulated in response to TGFβ1 treatment are involved in hippo signaling, Wnt signaling, focal adhesion, neuroactive ligand-receptor interaction, and pathways specific to cancer." (PMID 27144026, 2016). "It has been well characterized that transforming growth factor-beta 1 (TGF-β1) is a potent inducer of EMT during cancer pathogenesis." (PMID 27509259, 2016). "This marker plays a critical and dual role in the progression of human cancer and ithat TGFB1 positive patients showed remarkably longer survival than the others." (PMID 27463005, 2016). "Transforming growth factor β (TGF-β) is a critical protein in the regulation of several cancer phenotypes and keratinocytes of TGFβ1-null mice exhibit genomic instability." (PMID 27248179, 2016). "These dual TGFβ1 effects depend on the status of cancer cells and on the intracellular signalling events evoked upon the binding of its receptors." (PMID 27655713, 2016). "First, we will review briefly the integrin-dependent activation of latent-TGFβ1 and those integrins that are candidates for the activation of TGFβ1 in cancer." (PMID 27515461, 2016). "In accord with this, a 15-fold increase in the TGFβR1 level was detected in the cancer samples, whereas TGFβ1 expression remained unchanged." (PMID 26987776, 2016). "The IPA analysis revealed β-catenin, NFκB (p65) and TGFβ1 as important cancer-related proteins in these pathways." (PMID 28503055, 2016). "Specific ablation of TGFβ1 signaling has also been achieved in DC that have been utilized for the purpose of cancer vaccination." (PMID 27589814, 2016). "Cancer-derived exosomes deliver functionally active TGFβ1 to fibroblasts or to other precursors of myofibroblasts, such as mesenchymal stem cells and potentially mediate formation of a distinct form of myofibroblast." (PMID 26934553, 2016). "To address this, we analysed Dies1 expression, its regulation by promoter-methylation and miR-125a-5p overexpression, and its association with BMP-pathway downstream-effectors, in a TGFβ1-induced EMT-model, cancer cell-lines and primary samples." (PMID 27721458, 2016). "Clinical trials targeting TGFβ1 in cancer patients are also reviewed, and strategies for future therapeutic interventions that build on our current understanding of immune regulation by TGFβ1 are discussed." (PMID 27589814, 2016). "Collectively, these results suggest that lithium reduces the expression of TGFBIp in cancer cells by inhibiting the TGFβ1-Smad3 signaling pathway through the inactivation of GSK3β." (PMID 26857144, 2016). "Recent works have uncovered a mechanism by which, in cancer cells, TGFβ1 signals through NF-kB activation and nuclear translocation, ultimately leading to a rise in IL-6 secretion." (PMID 27851822, 2016). "TGFβ1 can promote angiogenesis and thus local activation of TGFβ by αv integrins in cancer is likely to promote the development of blood vessels." (PMID 27515461, 2016).
cancer (continued). "Of the integrins that can potentially activate TGFβ1, only αvβ3-specific antibodies and peptides have been used in humans as part of anti-cancer therapies but none has achieved significant clinical success." (PMID 27515461, 2016). "In the present study, we used a TGFβ1-induced EMT model, epithelial cancer cell lines and cancer samples to dissect the mechanisms underlying Dies1 expression and disclose its role in epithelial carcinogenesis." (PMID 27721458, 2016). "Three proteins of interest, β-catenin, NFκB and TGFβ1 were identified as being cancer-related proteins in the cell to cell signaling and organismal injury and abnormalities pathways." (PMID 28503055, 2016). "We propose that LRG potentiates the effect of TGFβ1 in cancer cells whose growth is suppressed in the presence of TGFβ1." (PMID 25826092, 2015). "TGFβ1, a multifunctional cytokine, is aberrantly over-expressed in various types of cancer cells and is involved in cell proliferation, migration, invasion, and metastasis." (PMID 25149540, 2014). "Changes in expression levels of EGF and the TGFβ1 can disrupt this homeostasis and promote the cancer progression." (PMID 25909813, 2014). "After verifying the biological meaning of the low-cost paths, the signal TGFβ1- TGFβR1- SMAD2/3- SMAD4- AR-OCIAD2 was discovered and explained TGFβ's stimulation on OCIAD2 expression in cancer." (PMID 24949437, 2014). "Transforming growth factor (TGFβ1) is a pleiotropic cytokine which contributes to wound healing, angiogenesis, fibrosis and cancer." (PMID 25162823, 2014). "The purpose of using hSMAD3 gene delivery was to provide the therapeutic effect of TGFβ1, but with lower adverse effects of fibrosis, cancer and infections." (PMID 25236373, 2014). "We then cultured carcinoma cells with TGFβ1 (1 ng/mL) overnight and found increased phosphorylated AKT in cells with DNIIR compared to those without DNIIR." (PMID 25280532, 2014). "Of the three known TGFβ isoforms, TGFβ1 seems to be directly involved in mediating the metastatic activity of cancer cells." (PMID 23840350, 2013). "In the present study, carcinoma cells and CAFs surrounding cancer nests markedly expressed TGFβ1 and HGF in ESCC when compared with that of precancerous lesions, particularly at the invasive edges of the carcinoma." (PMID 24137336, 2013). "The possibility of using TGFβ1 SNPs as predictive biomarkers in other kinds of cancer has been studied by others." (PMID 23840350, 2013). "Several studies demonstrated that TGFβ1 signaling components, including TGFβRII, are often lost in human cancer." (PMID 23951322, 2013). "The transcription of several key inflammatory factors, including IL1β, IL6 and TGFβ1, was induced in the carcinomas of both mice." (PMID 23526950, 2013). "The compound AP 11014, currently in advanced preclinical studies, specifically targets the TGFβ-1 mRNA and has been shown to significantly reduce TGFβ-1 secretion in multiple cancer cell lines, impeding TGF-β1-induced immunosuppression." (PMID 27340590, 2012). "Two functional polymorphisms at positions +869 T>C (rs1800470) and +915 G>C (rs1800471) in the signal protein sequence of the TGFB1 gene have been related to cancer progression and patient’s survival in several types of cancer." (PMID 23029430, 2012). "CAF from low-grade but not high-grade carcinomas required insulin-like growth factor 1 and transforming growth factor beta 1 to stimulate carcinoma growth." (PMID 23056402, 2012). "Transforming Growth Factor Beta-1 (TGF-β1) is a pleiotropic cytokine that is of central importance in wound healing, inflammation, and in key pathological processes including cancer and progressive tissue fibrosis." (PMID 21991303, 2011). "Our findings now additionally suggest that cancer cell response to TGFβ1 is regulated by material interactions with HA." (PMID 20107512, 2010). "Single nucleotide polymorphisms (SNPs) of the TGFB1 and VEGF genes have been associated with risk and progression of many cancers." (PMID 19835575, 2009).
cancer (continued). "With dual role in cancer development, there is great interest in analyzing the role of genetic variation in TGFB1 in cancer progression and patient survival." (PMID 19566948, 2009). "Pharmacological manipulation of TGFβ1 by PPARγ activators can be applied for treating TGFβ1-induced pathophysiologic disorders such as cancer metastasis and fibrosis." (PMID 18615188, 2008). "Cluster B (development) contains all the development and cancer genes with the exception of TGFB1 (which is in cluster A), together with ATOH1 (annotated as 'development')." (PMID 16438716, 2006). "With regard to the circulating levels of CD105, TGFβ1, TGFβ3 and the receptor–ligand complexes, the results indicate that except for TGFβ1, the levels of the other molecules were markedly elevated in cancer patients compared with controls." (PMID 12778073, 2003). "The levels of CD105/TGFβ1 complexes were significantly increased in patients with cancer, and were inversely correlated with node involvement (r=−0.26, P=0.0330)." (PMID 12778073, 2003). "Among all lncRNA variants analyzed, and in the absence of KCNIP4-IT1 data in TCGA, we conclude that VIM-AS1 expression can be distinguished by its correlation with TGFB1 expression, in addition to being upregulated in response to TGF-β in various cancer cell lines." (PMID 41556346, 2026). "Interestingly, when TGFβ1 was blocked with a TGFβ1-neutralizing antibody, the cancer-killing efficiency of CD8+ T cells significantly increased, along with an increased proportion of IFN-γ+ and GZMB+ CD8+ T cells." (PMID 39897553, 2025). "EV signatures (EVsig) also show strong positive associations with canonical EMT transcription factors (TWIST1, SNAI1/2), immunosuppressive genes (PD-L1, TGFB1), MMPs, and cancer stem cell markers (CD44, ALDH1A1), suggesting interconnected mechanisms of immune evasion and metastatic capability." (PMID 41154440, 2025). "Particularly noteworthy is our identification of TGFB1 and CCL11 as risk‐promoting factors (OR = 1.173, p = 0.020; OR = 1.192, p = 0.003), which aligns with existing knowledge of their biological functions in cancer development." (PMID 40682474, 2025). "And in cancer-associated fibroblast (CAF)-rich tumors, such as breast cancer, lung cancer and colorectal cancer, setanaxib more effectively counteracts CAF-mediated immunosuppression than TGFβ1 inhibition, which is a key regulator of the CAF phenotype." (PMID 40424719, 2025). "Such C3 marker upregulation is concordant with our previous observations of cancer cell-induced plasticity of C1 cultures, whereby C1 cultures treated with CM from TGFβ1-/2-secreting PC3 cells significantly upregulated C3/myofibroblast markers in a manner dependent on fibroblast TGFβR activity." (PMID 41327318, 2025). "Moreover, in TA33.Combo-treated mice, we observed reduced co-localization of cancer cell identity transcripts with protumoral transcripts (e.g., Tgfb1, Vegfa, Pdgfb)." (PMID 40216735, 2025). "However, plasma Tgfβ1 levels in all three cancer types exhibited a significant positive correlation with the MO-/PMN-MDSC ratio." (PMID 41360769, 2025). "Spheroids are useful tools for proof-of-principle CAR-NK cell testing, as shown recently in the context of CAR-NK-92 cells secreting a peptide that blocks TGFβ1 signaling, which were tested using multicellular cancer spheroids and cancer-derived fibroblasts from patients with pancreatic cancer." (PMID 40519903, 2025). "We found that knockdown of TGFβ1 significantly inhibited the cancer-promoting ability of TBX3." (PMID 39897553, 2025). "The upregulation of multiple lineage plasticity genes, including basal (Trp63, Krt5 and Krt14), metastasis (Snai2, Tgfb1 and L1cam), and stemness (Sox2, Mecom and Sox6) markers was induced by LKB1 loss, further supporting the enhanced cancer cell state plasticity by LKB1 loss." (PMID 39743630, 2025).
cancer (continued). "Interestingly, Lrrc15 and Tgfb1 levels in HCC1954 stroma remained constant, while TGFB1 expression was increased in treated LRRC15-null HCC1954 cancer cells." (PMID 41022704, 2025). "It enhances TGFβ1 expression and promotes cancer cell migration and invasion." (PMID 41437175, 2025). "BMP4’s known role in promoting differentiation and anti-proliferative effects in GBM CSCs35,36 and its reciprocal inhibition with TGFβ1 in other cancer types may explain this inverse regulation." (PMID 40894044, 2025). "Additionally, the TGFB1 gene promotes epithelial-mesenchymal transition, facilitating the metastasis of cancer cells." (PMID 41305721, 2025). "TGFB1, a cytokine with regulatory functions, has been reported in the literature to exhibit both stimulatory and inhibitory properties in regulating tissue homeostasis, developmental processes, tissue remodeling, and disease states such as cancer." (PMID 40256740, 2025). "TGFβ1 plays an immune suppressive role across various cancers." (PMID 40725832, 2025). "Having thus far only evaluated TGFβ3’s contribution to tumor suppression, we wanted to address the other, pro-metastatic arm of the TGFβ family’s dual role in cancer – a concern due to frequent extrapolation of data relating to TGFβ1’s role in promoting breast cancer to TGFβ3." (PMID 38831405, 2024). "Additionally, in HCC, infiltrating Treg cells have been implicated in triggering the TGFβ1 signaling pathway and promoting the EMT of cancer cells during tumor hematogenous dissemination, potentially increasing the invasive potential of HCC cells." (PMID 39683528, 2024). "TGFB1 facilitates the progression and evasion of cancers, suppressing antitumor immune responses." (PMID 38748299, 2024). "Furthermore, ESCA patients tend to exhibit elevated serum levels of TGFβ1 compared to healthy controls, which generally goes down following radiotherapy, highlighting its relevance to cancer progression." (PMID 39796131, 2024). "Furthermore, PDE2A expression in most cancers was positively associated with PDCD1, EDNRB, ADORA2A, TGFB1, and especially C10orf54." (PMID 39699377, 2024). "However, another critical regulator in cancer, transforming growth factor-beta 1 (TGF-β1) has a paradoxical role in cancers and was upregulated when Nav1.5 was inhibited in cardiac myocytes and fibroblasts." (PMID 39060933, 2024). "TGFβ1 is an important regulator of immune tolerance and homeostasis whose inhibition may contribute to the eradication of cancer and cardiovascular deteriorations." (PMID 39062148, 2024). "Transforming growth factor-β1 (TGFβ1) is a multifunctional cytokine that, based on environmental or cellular context, leads to a diversity of cellular responses, including cell proliferation, differentiation, migration, apoptosis, and cancer progression." (PMID 39062148, 2024). "Estrogen receptor-positive breast cancer patients may benefit from high levels of TGFB1 expression due to the repression of estrogen receptor signaling, inhibition of proliferation, and induction of apoptosis in cancer cells." (PMID 39468555, 2024). "In addition, a strong correlation has been seen between the regulation of the MAPK activity pathway and the invasion and metastasis of cancer by transforming growth factor beta 1 (TGF-β1), EGF, and its related receptor, EGFR." (PMID 39507759, 2024). "In a previous study, platelet-derived TGFβ activated the Smad and NFκB pathways in cancer cells, resulting in EMT and enhanced metastasis in vivo; inhibition of NFκB signaling in cancer cells or ablation of TGFβ1 expression in platelets protected against lung metastasis in vivo." (PMID 38201575, 2023). "This indicates that TGFB1 might play essential roles in the regulation of the immune response to these cancers." (PMID 37925591, 2023). "Another important regulator of cancer development is transforming growth factor beta 1 (TGF-β1)." (PMID 37653930, 2023).
cancer (continued). "ActA and TGFβ1 may also have independent and opposite effects, such as on the expression of p21 in these cancer cells." (PMID 36717814, 2023). "Taken together, one can see that the mast cell-derived chymase may promote not only cancer development but also cancer metastasis through the activation of TGFβ1, MMP-9, and VEGF." (PMID 37175975, 2023). "In terms of cancer progression, TGFβ1 induces EMT through activation of cell motility and invasion." (PMID 36639705, 2023). "Likewise, signalling molecules tumour necrosis factor (TNF), transforming growth factor beta (TGFB1), and C-X-C motif chemokine 12 (CXCL12) were prominent drivers of downstream gene expression associated with multiple cancer hallmarks." (PMID 37370765, 2023). "Importantly, miRNA-195 and miRNA-497 effectively targeted SMURF2 and increased TβRI levels in TGFβ1-treated cancer cells." (PMID 37568787, 2023). "Here, platelet TGFβ1 is a general driver of cancer cell epithelial-to-mesenchymal transition (EMT) via activation of the Smad2/3 and NF-kB pathways, and of HCC growth both in vitro and in vivo, where it also suppresses cancer cell Krueppel-like factor 6 (KLF6) expression." (PMID 38116017, 2023). "In addition, CD96, CD244 have been identified as new checkpoint receptor targets for cancer immunotherapy, and TGFβ1 has been found to play a key role in the EMT process in ccRCC." (PMID 37679715, 2023). "To test whether our findings could be generalized to solid tumors, we analyzed the predictive role of TGFB1 in patients with cancer who received ICB therapy." (PMID 37925591, 2023). "TGFβ1 also exhibits a cell-type- and context-dependent pleiotropic effect that promotes or inhibits cancer progression 21; hence, we suggest that this could explain, at least partially, the pleiotropic role of NDRG1." (PMID 36594086, 2023). "ITGA4 and TGFB1 have been found to be co-expressed in four cancer studies." (PMID 37967122, 2023). "An increase in the external TGFβ1 levels may lead to uncontrolled fibrosis, which raises the question of whether a long-term cancer treatment involving betulin and its derivatives that elevate TGFβ1 protein levels is safe." (PMID 38132468, 2023). "5-FU-miR-15a was also shown to significantly inhibit the expression of Yap1, Bcl2, Il6, and Mmp9, both alone and during treatment with TGFβ1 in murine and human Pancreatic Stellate Cells, suggesting the reduced proliferation and migration of pancreatic stellate and cancer cells." (PMID 38139352, 2023). "TGFB1 might regulate the immune microenvironment in a cancer-type-specific manner, which could be applied in the development of new targeted drugs for immunotherapy." (PMID 37925591, 2023). "Therefore, MIR100HG regulates the extent of TGFβ signaling by promoting TGFβ1 autoinduction and secretion in carcinomas." (PMID 38042769, 2023). "In addition, TGFβ1 and TGFβ3 were negatively associated with MATH, which is prevalent in most cancer patients and is a major driver of acquired resistance to cancer therapy." (PMID 36119489, 2022). "Fetuin-A is a multi-functional protein, including as an important inhibitor of ectopic calcification acting on the systemic level, one of the steps that can be active in disease progression in axial SpA patients and a TGFb1 antagonist in advanced cancers and fibrosis." (PMID 37362028, 2022). "The role of CAF-derived TGFβ-1 as an extrinsic factor has been identified in different cancers, including cutaneous squamous cell carcinoma (cSCC) and basal cell carcinoma (BCC), the two main types of NMSC, in which it can induce resistance to different therapies." (PMID 36338755, 2022). "Furthermore, exosomes upregulated fibronectin on LSECs through delivering TGFβ1, which facilitates cancer cell attachment to the liver microenvironment." (PMID 36430471, 2022).